APP (amyloid beta precursor protein)
Diseases named in the same sentence as APP in open-access papers (continued):
Sharing a sentence is not in itself a finding about the gene and the disease.
memory impairment (continued). "YY-1224 appeared to be more effective than Gb against cognitive dysfunction and Aβ pathology in APP/PS1 Tg mice as well as against Aβ-induced memory impairment via microglia polarization." (PMID 28449688, 2017). "Our results demonstrated the pronounced effects of YXQN extract, not only on ameliorating cognitive and memory impairment, but also on mitigating the critical pathology in APP/PS1 mice." (PMID 28603494, 2017). "We observed that STZ-induced episodic and working memory impairment was significantly worsened in APP/PS1 mice." (PMID 26156287, 2016). "Both ethosuximide and brivaracetam reduce mouse SWDs, but only brivaracetam reverses memory impairments in APP/PS1 mice." (PMID 25945128, 2015). "As noted, two previous studies in J20 and APP/PS1 mice have shown clear benefits of levetiracetam in reversing memory impairments in this model, suggesting that targeting SV2A alleviates AD symptoms across AD models." (PMID 25945128, 2015). "Mice expressing human β-amyloid precursor protein (APP), TAU and/or PSEN1 genes harboring familial AD-linked mutations develop AD pathological hallmarks, neuroinflamation and memory impairments." (PMID 26379494, 2015). "In this study, we mimicked the prodromal stage of AD using APP/PS1 mutated transgenic mice, and proved the protective effect of CUR on the memory impairment and bone loss via anti-oxidative character." (PMID 26186010, 2015). "The aims of this study were to determine the miRNA expression pattern and the role of let-7d-APP in aged rats with learning and memory impairment induced by isoflurane." (PMID 25799420, 2015). "We first determined the progression of AD-like pathology and memory impairments in APP/PS1 mice using immunohistochemistry and behavioral analysis." (PMID 24974208, 2014). "In the present study, exercise during early periods was able to inhibit HFD-induced memory impairment in APP-HFD mice." (PMID 24023774, 2013). "Consistent with previous reports, APP mice develop memory impairments by 8–9 months when compared to age-matched WT or CCL2 littermates (T4 and T5)." (PMID 19593388, 2009). "APP and CCL2 mice have normal memory function at 2–3 months of age, whereas APP/CCL2 mice have already developed memory impairment." (PMID 19593388, 2009). "Notably, this test revealed that oral administration of dl-PHPB for 3 months significantly ameliorated memory impairment in APP/PS1 mice." (PMID 40343003, 2025). "5XFAD mice contain the APPswe mutation with the Florida (I716V) and London (V717I) mutations of APP, together with the M146L and L286V mutations of PS1, resulting in accelerated accumulation of amyloid aggregates, brain pathology, and memory impairment, at a younger age." (PMID 39216535, 2024). "Similarly, the RAF inhibitor sorafenib reversed memory impairment and decreased the expression of APP, Cox-2, and iNOS in the brain of an AD transgenic mouse model, highlighting the potential of targeting RAF1." (PMID 39000011, 2024). "The mice were tested using MWM and Y maze experiments to verify whether quercetin could enhance memory impairment in APP/PS1 mice." (PMID 39233848, 2024). "In addition, they also prevent Tau protein phosphorylation and amyloid precursor protein (APP) accumulation in the brain; those factors are closely linked to depression and memory impairment." (PMID 39574138, 2024). "Overexpressing Nav1.1 in APP mice rescued network imbalance, Gamma power, and memory impairment." (PMID 38474398, 2024). "Furthermore, in APP-overexpressing transgenic mice, an increase in caspase-3 activity was observed at the onset of memory impairment." (PMID 39125907, 2024). "More recent studies have confirmed that both Aβ and Tau could propagate the disease and induce synaptic and memory impairments via the amyloid precursor protein (APP)." (PMID 38203429, 2023).
memory impairment (continued). "Although potential memory enhancement by HDAC inhibitors may contribute to behavioral improvement, it is clear that the Aβ and hyperphosphorylated tau levels correlate more strongly with memory impairment in APP/PS1 mice." (PMID 36708130, 2023). "Since the memory impairment in 5xFAD mice is mainly associated with amyloid precursor protein (APP) overexpression, we then compared the effects of TNEA and its composing acupoints on the reduction of APP and its C-terminal fragments (CTFs)." (PMID 36732771, 2023). "In addition, our previous study shows that miR-204-3p alleviates memory impairment by mitigating synaptic dysfunctions and oxidative stress in APP/PS1 mice." (PMID 37192007, 2023). "Collectively, we have, for the first time, demonstrated that hops extract protects against Aβ-induced senior osteoporosis primarily by ameliorating memory impairment, enhancing BMD and trabecular bone structure and improving osteoblastic MC3T3-E1 cell activities in APP/PS1 mutated transgenic mice." (PMID 36677642, 2023). "As working memory is a central component of cognitive function and is particularly susceptible to AD29,30, we asked whether anesthesia produces a lasting disruption to SWM in APP/PS1 mice before the appearance of innate memory impairments." (PMID 37919286, 2023). "As a result, the COX-2 inhibitor (meloxicam) significantly inhibited memory impairment, neuronal necrosis, oxidative stress, and inflammatory response, and significantly downregulated the expression of APP, Aβ, COX2, whereas it significantly increased exploring behavior." (PMID 35682823, 2022). "In addition, the activation of the cholinergic circuit from the MS and VDB to the hippocampus using chemical genetics is able to improve learning and reduce memory impairment in APP/PS1 mice." (PMID 35418161, 2022). "To address whether ECH could improve memory impairments in APP/PS1 mice, we tested the mice using the Morris water maze and nest building tests, which assessed spatial learning and memory function." (PMID 35665898, 2022). "Consistent with our prediction, previous studies have shown that therapeutic elevation of selenium in 3xTg-AD mice, which express mutant PS1 in addition to mutant APP and tau, effectively combats hippocampal-dependent learning and memory impairments, as well as behavioral phenotypes." (PMID 35449212, 2022). "In addition, APP/PS1/CB1R–/– mice (APP/PS1 mice with additional CNR1 knockout) developed accelerated memory impairments in the two-object recognition test." (PMID 36117622, 2022). "Aβ1-42 and p-Tau were decreased by MTHF supplementation, and 5-MTHF may slow Aβ accumulation and p-Tau production by reducing APP levels and glycogen synthase kinase-3β activation, alleviating memory impairment." (PMID 36554305, 2022). "In addition, memory impairment in APP/PS1 mice can be attenuated using chemical genetics-driven Ach cycle activity of the cholinergic circuit." (PMID 35418161, 2022). "In this study, MO was found to improve Aβ load, synaptic proteins, neurodegeneration, and neuroinflammation which together might explain the amelioration of behavioral, cognitive, learning, and memory impairments in APP/PS1 mice treated with MO." (PMID 36296969, 2022). "Thus, Aβ-Teffs decreased glucose uptake in the hippocampus region of APP/PS1 mice paralleled their abilities to accelerate memory impairment." (PMID 34798897, 2021). "MITOL deletion itself did not cause any defects in these memory functions, whereas APP/PS1 mice developed mild memory impairments." (PMID 33580194, 2021). "Notably, patients in prodromal phases of AD show memory impairments, depression, anxiety and reduction of olfaction function, as we observed in APP/PSEN1-Tg mice at 3 and 6 months of age." (PMID 33795014, 2021). "This study also showed that TA treatment could significantly improve the memory impairment of APP/PS1 mice." (PMID 34671194, 2021).
memory impairment (continued). "In yet another transgenic mouse strain, the Tg 2576 APP transgenic mice, and in a double mutant including both the APP and a PSEN mutation, vaccination against Aβ afforded protection from memory impairment, in the presence of reduced—but still substantial—Aβ deposits." (PMID 33260956, 2020). "First, we determined whether the EA stimulation could delay/reverse learning and memory impairment in APP/PS1 transgenic mice." (PMID 32908486, 2020). "Stigmasterol was reported to participate in axon and dendrite development, the modulation of synaptic transmission, reduction of amyloidogenic amyloid precursor protein (APP) processing, inhibition of acetylcholine esterase, and amelioration of memory impairment." (PMID 32908557, 2020). "To determine whether NPS alteration is responsible for the development of memory impairment in APP/PS1 mice, we conducted c-Fos immunostaining and counted the density of active neurons." (PMID 31293402, 2019). "Moreover, JuA suppresses SD-induced enhancement of mEPSCs and prevents memory impairment in APP/PS1 mice." (PMID 30872728, 2019). "A probe test performed 24 h after the final training trial revealed that the untreated APP/PS1 mice exhibited no preference toward the target quadrant, which indicated significant memory impairment, whereas the lentivirus-treated APP/PS1 mice performed similarly to the WT C57BL/6 mice." (PMID 31143112, 2019). "Interestingly, the activation of GSK3β is also implicated in amyloidogenesis by inhibiting the secretory cleavage of APP, increasing the production of Aβ and leading to memory impairment in animal models." (PMID 30971876, 2019). "Taken together, these data indicated that DNLA could improve learning and memory impairment in APP/PS1 mice." (PMID 30618767, 2018). "Furthermore, an NMR-based metabolomics study of the transgenic amyloid precursor protein/presenilin 1 (APP/PS1) mouse model of Aβ pathology found that these mice had significant hypothalamic metabolic abnormalities prior to memory impairment." (PMID 30568576, 2018). "A pioneer study demonstrated that memory impairments in APP-overexpressing (J20) mice can be rescued by tau deletion; it was suggested that tau depletion results in an amelioration of APP-induced hyperactivity of hippocampal neurons and therefore, cognitive improvement." (PMID 29545742, 2018). "Together, these results indicated that chronic treatment of ICS II could ameliorate the spatial learning and memory impairments in APP/PS1 transgenic mice." (PMID 28337142, 2017). "Furthermore, Rg1 was shown to repair hippocampal long-term potentiation (LTP) and improved memory impairment in APP/PS1 mice, likely through facilitating the clearance of AD-associated proteins and activating the BDNF-TrkB pathway." (PMID 29204248, 2017). "In conclusion, the present study demonstrates that ICS II could attenuate spatial learning and memory impairments in APP/PS1 transgenic mice." (PMID 28337142, 2017). "Thus, we cannot exclude the possibility that PYR supplementation would have been beneficial in 12-month-old APP/PS1 mice with more robust memory impairment." (PMID 27014054, 2016). "However, several studies have shown that APP plays a positive role in memory, raising the possibility that aside from Aβ toxicity, APP loss-of-function may participate in AD, particularly during the early stages of the disease characterized by memory impairment." (PMID 28008309, 2016). "Downregulation of let-7d might contribute to isoflurane-induced learning and memory impairment through upregulating its target APP, and increasing the production of Aβ subsequently." (PMID 25799420, 2015). "Application of an antagonist of Aβ has been shown to improve memory impairment in APP Tg mice." (PMID 24447795, 2014).
memory impairment (continued). "Since the degree of memory impairment in APP-HFD+Ex0–10 mice was the same as that in APP-HFD mice, we speculated that the increase of soluble Aβ oligomer by HFD after finishing exercise might be sufficient to lead to memory loss." (PMID 24023774, 2013). "Mice engineered to over express mutant APP exhibit increased APP deposition and memory impairment." (PMID 24349472, 2013). "The results suggested that chronic caffeine treatment may reverse memory impairment in PS1/APP transgenic mice, and BDNF and its receptor TrkB, may be involved in this process." (PMID 23900282, 2013). "Increased inflammatory responses, down-regulated BDNF and TrK B expressions, and up-regulated APP and p75 expressions may contribute to memory impairment after subacute or chronic IL-1 administration." (PMID 23651534, 2013). "Moreover, ablation of PrPc enhances cognitive function in transgenic mice overexpressing mutant amyloid precursor protein (APP) gene (APPswe and PS1ΔE9) preventing premature death of neurons and memory impairment." (PMID 23267328, 2012). "This hypothesis has been supported by cell-culture viability assays and through numerous animal experiments, where several independent investigations have described memory impairment in APP transgenic mice to precede the detection of Aβ depositions." (PMID 21085663, 2010). "However, APP/CCL2 mice show more severe memory impairments as determined by errors and latencies at T4 and T5, when compared to APP, CCL2, or WT mice." (PMID 19593388, 2009). "The data support the idea that CCL2 is a co-factor in Aβ-induced memory impairment for APP mice." (PMID 19593388, 2009). "Thus, memory impairment in APP mice may arise from an interplay between impaired consolidation‐dependent plasticity and insufficient reactivation of memory‐encoding ensembles during memory recall." (PMID 41307180, 2025). "Therefore the inhibitory effect of INH on Mao-b may also contribute to the therapeutic effect on memory impairment in APP/PS1 mice." (PMID 36743440, 2023). "Importantly, inhibiting PV neuron activity at an early stage or stimulating PV neuron activity at a later stage, both restored Morris water maze performance in APP/PS1 mice, suggesting that both states, hyperexcitable first and hypoexcitable later, are causally linked to memory impairment in AD." (PMID 37419975, 2023). "Together, these results suggest that the combination of GB13 and GV24 points in the TNEA therapy may synergistically reduce the APP/CTFs levels via autophagic degradation and other unknown mechanisms, thus leading to the attenuation of memory impairment in 5xFAD mice." (PMID 36732771, 2023). "GSIs reduce the dendritic spine density in normal mice but not in APP-knock-out mice, suggesting that the accumulation of either CTFα or β or both may cause synaptic toxicity and a potential cause of memory impairment." (PMID 38204816, 2023). "Additionally, memory impairments can emerge in young APP mice before plaques accumulate." (PMID 37720546, 2023). "Here, we examined whether CLSPCOL is effective against the memory impairment of the APP/PS1 mice at an early phase, and the memory impairment, caused by the temporal disturbance of the cholinergic neurotransmission, that mimics a part of AD-linked neuronal abnormality." (PMID 35178248, 2022). "Thus, we conclude that Plk2 contributes substantially to localized amyloid plaque formation and mediates physiological activity-dependent amyloidogenic APP processing in the brain, and that suppressing this pathway can functionally rescue disease-relevant synaptic pathology and memory impairment." (PMID 31306446, 2019). "In conclusion, the present study reveals that 0.75 mg/day and 1.5 mg/day of caffeine for eight weeks is capable of reversing memory impairment in 12 month old PS1/APP transgenic mice, and BDNF and its receptor TrkB may be involved in the protective role of caffeine against memory impairment in AD." (PMID 23900282, 2013).
memory impairment (continued). "Compared with WT mice, APP/PS1 mice exhibited significantly prolonged escape latency in the Morris water maze (MWM) test, indicating that spatial learning and memory impairments are characteristic of AD." (PMID 41184271, 2025). "So, our experimental deadline was set at seven and a half months for APP/PS1 mice, guaranteeing that observable memory impairment and pathological damage on the hippocampus should be evident in the AD group." (PMID 40693114, 2025). "Behaviorally, APP/PS1 mice exhibit declines in learning ability, memory impairment, and increased anxiety—cognitive and emotional disturbances that closely mirror those seen in AD patients." (PMID 40822397, 2025). "By regulating different factors in the APP metabolic pathway, our study confirmed the role of FBXL16 in improving cognitive and memory impairments in AD." (PMID 39568047, 2024). "Inhibiting PV neuron activity early or stimulating it later restores Morris water maze performance in APP/PS1 mice, linking both states to memory impairment in AD." (PMID 38474398, 2024). "In this study, APP/PS1 mutated transgenic mice were used to mimic the SOP condition, and we found that there was Aβ deposition not only in the brain but also in the femurs of APP/PS1 mice, which was an important trigger of memory impairment and osteoporosis." (PMID 36677642, 2023). "A previous preclinical study conducted on 3-month-old APP/PSEN1-Tg mice has further supported the connection between depressive- and anxiety-like behaviors, along with memory impairments." (PMID 37629191, 2023). "Ubiquitously co-expressing the human amyloid precursor protein and β-secretase (APP:BACE) in adult flies also results in the accumulation of Aβ peptides and memory impairment." (PMID 36744027, 2023). "Together, these findings suggest biphasic alterations in PV neuron activity during amyloidosis in APP/PS1 mice and potentially different mechanisms of memory impairment at different disease stages." (PMID 37419975, 2023). "Together with the present findings acquired in old APP/PS1 mice that harbor hippocampal Aβ deposits, these observations suggest that RUN-associated hippocampal neuronal hyperactivity develops with plaque deposition and may reflect a physiological correlate of memory impairment." (PMID 36471155, 2022). "The APP/PS1 double transgenic mice showed typical Aβ pathology and memory impairment in an age-dependent manner." (PMID 35095466, 2021). "For example, the microglia AD genes, including APP, CLU, BACE2, and BIN1, are specifically enriched for other diseases such as neurofibrillary degeneration, Parkinson’s dementia, and aging memory impairment." (PMID 34044854, 2021). "The plasma samples of normal C57BL/6 mice, APP/PS1 double transgenic mice, and scopolamine-induced memory impairment mice were collected and were analyzed to compare the difference of βCBs in different physiological states." (PMID 35095466, 2021). "Twenty-eight weeks old APP/PS1 double-transgenic mice showed cognitive and memory impairments in a MWM test, which was ameliorated by Boc2 treatment." (PMID 32331524, 2020). "Inaddition, the activation of GSK3β inhibits the secretory cleavage ofthe amyloid precursor protein (APP), elevating the production ofthe Aβ peptide, thereby leading to memory impairment inanimal models." (PMID 31354196, 2019). "Heneka and colleagues showed that APP/PS1/NLRP3−/− and APP/PS1/Casp-1−/− mice were largely protected from memory impairment in APP/PS1 mice." (PMID 29495433, 2018). "Eight-month-old APP/PS1 transgenic mice exhibit severe learning and memory impairment, and represent an animal model of AD." (PMID 29712923, 2018). "We report here that inhibition of PDE7 reversed hippocampal and cortical Aβ-induced memory impairments, restored CREB phosphorylation via increasing intracellular cAMP levels, and increased the hippocampal neurogenesis in transgenic APP/PS1 mice." (PMID 29458418, 2018).